NRP1 (neuropilin 1)
Diseases named in the same sentence as NRP1 in open-access papers (continued):
Sharing a sentence is not in itself a finding about the gene and the disease.
tumor (continued). "In tumor blood vessels, two key molecules (neuropilin-1, NRP-1, and neuropilin-2, NRP-2) can regulate tumor tissue vasculature permeability and enhance permeability through the interaction between the C-end Rule (CendR) motif and neuropilin." (PMID 31346334, 2019). "As NRP1 is overexpressed in several cancer types, it appears as an attractive therapeutic target both for reaching the tumor bed and for blocking tumor-cell expansion in a variety of cancers." (PMID 31652529, 2019). "A subsequent study described the importance of VEGF/VEGFR2/NRP1 signaling in the survival of glioma CSCs and tumor growth." (PMID 30678134, 2019). "NRP-1 depletion suppressed tumor growth and liver metastasis and miR-141 mimics inhibited the growth of established tumors in mice." (PMID 31572065, 2019). "These peptides bind to tumor cell NRP1 to increase drug uptake, which consequently boosts the antitumor effect." (PMID 31208428, 2019). "To examine the effecte of NRP1 in microenvironment of in vivo for tumor cell, we constructed the mouse tumor-bearing model and treatment of mice." (PMID 31417646, 2019). "In a melanoma model, conditional knock out of Nrp-1 resulted in impaired tumor growth with a decrease in intratumoral Tregs." (PMID 31681327, 2019). "Lebein, a snake venom disintegrin from Macrovipera lebetina inhibits tumor angiogenesis by reducing the expression of NRP1 and VEGF in a quail embryonic chorio-allantoic membrane system as well as in a human colon adenocarcinoma xenograft mouse model." (PMID 30717262, 2019). "NRP1 exhibits multiple functions such as promoting cell migration and angiogenesis, two properties that justify targeting NRP1 for tumor-inhibition." (PMID 31652529, 2019). "Such NRP1-specific tumor targeting peptides effectively enhance the uptake of various therapeutic agents." (PMID 30717262, 2019). "Xenograft tumor models were established to assess the effects of NRP-1 depletion on tumorigenesis and liver metastasis, and therapeutic effects of miR-141 on tumor growth." (PMID 31572065, 2019). "In the same manner, sNRP1, functioning as natural ligand trap, inhibits the interaction of PlGF-2 and VEGF with their specific receptors and with membrane NRP1 expressed by tumor or normal cells." (PMID 31216652, 2019). "In this study, we have compared the various tumor-inhibitory effects following transient RNAi-mediated depletion of NRP1, NRP2 or GIPC1 either alone or in combination, in PDAC cell lines with different expression levels." (PMID 31664117, 2019). "T cells from spleens and tumour-draining lymph nodes (TdLN) of the same mice were examined in parallel for Nrp-1 expression." (PMID 31350404, 2019). "On the contrary, EG00229 binds to the b1 domain of NRP1 and disrupts the angiogenic signaling in tumor-endothelial cells as well as autocrine signaling in tumor cells." (PMID 31840081, 2019). "iRGD-PTX-PCL-PVP showed superior cytotoxicity and cellular uptake of the particles, which indicated that the iRGD peptide contributes to the interaction of the nanoparticles with tumor cells through NRP-1 overexpression on the cell surface." (PMID 31346334, 2019). "A role was demonstrated for NRP1 in tumor-specific uptake of Cltx and, notably, expression of NRP1 on tumors positively correlated with the antitumor activity of ER-472." (PMID 31208428, 2019). "Specifically, NRP1 stimulated a JNK-signaling pathway that resulted in the upregulation of alternative effector kinases (EGFR or IGF1R) that sustained tumor growth." (PMID 30678134, 2019). "The expression of NRP1 in each group of tumor tissues was confirmed by immunofluorescence and found to be the same as in vitro." (PMID 31417646, 2019). "Neuropilin-1 is a transmembrane protein also overexpressed in many tumors displaying growth-promoting functions and mediates tumor-initiating properties." (PMID 31847321, 2019).
tumor (continued). "High plasma VEGF-A and low tumor NRP1 expression turned out to represent strong biomarkers predicting better clinical outcomes in patients with advanced gastric cancer, treated with bevacizumab." (PMID 31027288, 2019). "A strong positive correlation was noted between tumor NRP1 expression and ER-472 antitumor activity in the 3 initial xenograft models." (PMID 31208428, 2019). "In tumors, NRP1 is involved in evading the control by the immune system and also in angiogenesis and formation of tumor-characteristic vasculogenic mimicry (VM) vessels that significantly contribute to resistance to antiangiogenic therapy." (PMID 30717262, 2019). "These recruited bone marrow cells consist of a neuropilin-1 expressing a sub-population of monocytes and contribute to the stabilization and normalization of tumor vessels by promoting coverage of tumor vessels by mural cells." (PMID 30696103, 2019). "In this study, we directly compare the various tumor-inhibitory effects of transient RNAi-mediated depletion of NRP1, NRP2 and GIPC1, alone or in combination, in a set of cell lines with different expression levels." (PMID 31664117, 2019). "For example, upon SEMA3A overexpression in tumor cells, it selectively expanded the population of M1-like pro-inflammatory macrophages derived from NRP1+ monocytes, which further led to the recruitment of NK and CD8+ cytotoxic T cells." (PMID 30658382, 2019). "It was found that NRP1 is furthermore required for Treg stability, tumor infiltration and local suppression of immune response." (PMID 31027288, 2019). "VEGF also plays an important part in Treg cell infiltration, since deficiency of neuropilin-1 (NP-1), a factor that responds to VEGF, impaired Treg cell infiltration and decreased tumor growth in spontaneous melanoma models." (PMID 31535086, 2019). "Tumor tissue penetration is triggered by peptide binding to integrins through the interaction of the CendR motif with NRP-1." (PMID 31346334, 2019). "In particular, while it has been shown by different groups that SEMA3A can attract NRP1-expressing tumor-infiltrating monocytes, data diverge on the functional role of these cells." (PMID 30658382, 2019). "Potency was significantly reduced by treatment with NRP1 blocking antibodies or knockout in tumor cells, confirming a role for NRP1-binding in ER-472 activity." (PMID 31208428, 2019). "At the same time, EG00229 will disrupt VEGF–NRP1 axis leading to the inhibition of VEGF/VEGFR2/NRP1-mediated proangiogenic signaling pathways in endothelial cells and VEGF/NRP1/Ras-mediated autocrine activation of tumor cell growth." (PMID 31840081, 2019). "The role of NRP1 expressed by TAMs in controlling their entry into tumor hypoxic regions in response to Sema3A has been investigated." (PMID 31052281, 2019). "These T lymphocytes express high levels of PD-1, defining a subset of Nrp-1+PD-1hi TIL enriched with tumour-specific T cells." (PMID 31350404, 2019). "Neuropilin-1 (Nrp1), a co-receptor protein highly expressed on Treg cells has been involved in tolerance-mediated responses, driving tumor growth and transplant acceptance." (PMID 31068948, 2019). "We then further assessed tumour reactivity of Nrp-1+PD-1hi and Nrp-1−PD-1+ TIL by measuring CD107a expression, a marker usually used to evaluate the degranulation capacity of CTL." (PMID 31350404, 2019). "Since NRPs can associate with diverse receptors into holoreceptors, they are promising targets for tumor therapies, and development of highly specific and highly potent NRP1 inhibitors is of outstanding interest." (PMID 30717262, 2019). "The synthetic NRP1-targeting peptide EG3287 blocks VEGF signaling and induces apoptosis of NRP1-expressing tumor cells expressing." (PMID 30717262, 2019). "In interacting adjacent cells, endocytosis of VEGF-A-VEGFR2 complexes is prevented by incorporation of trans-standing NRP1 into holoreceptor complexes, thereby regulating angiogenesis, tumor initiation and tumor angiogenesis." (PMID 30717262, 2019).
tumor (continued). "T cells express the neuropilin-1 and plexin-A4 sema3A receptors, and sema3A containing conditioned medium from such tumor cells was observed to inhibit the proliferation of these cells and their activation by anti-Cd3 antibodies." (PMID 30696103, 2019). "The Transwell method was used to investigate the effect of tumor microenvironment on the migration of A549 cells in different states of NRP1 expression." (PMID 31417646, 2019). "We have also observed that Nrp1 depletion from GAMs slows tumor progression and increases anti-tumoral immunity in a murine model of GBM." (PMID 32914058, 2018). "Strikingly, the presence of VEGFR2/NRP1 trans‐complexes correlated with reduced vessel counts and reduced vessel branching, along with reduced tumor proliferation, in both the mouse cancer model and human PDAC." (PMID 30027561, 2018). "We have shown in the GL261 model of murine GB that GAM-specific knockout of NRP1 slows disease progression by reducing tumor vascularization and inhibiting immunosuppressive TGFβ signaling." (PMID 30479695, 2018). "Ultimately, along with our knowledge of differential metabolism, this study suggests the potential of anti‐NRP‐1 therapy to limit tumor progression through modulation of metabolism." (PMID 30216699, 2018). "To correlate the presence of VEGFR2/NRP1 trans‐complexes to vessel parameters and tumor proliferation, we immunostained tumor samples for CD34 and Ki67." (PMID 30027561, 2018). "NRP1 is overexpressed on angiogenic blood vessels and tumor cells, and iRGD binding to NRP1 activates an endocytic pathway that leads to tumor penetration of iRGD, as well as drugs coadministered or conjugated with iRGD." (PMID 29888319, 2018). "The authors showed that blockade of Neuropilin-1 (Nrp-1) in vivo reduced TFGβ-mediated EndMT, fibrosis and tumor size." (PMID 29373514, 2018). "The observed correlation with genes characteristic of pro-tumorigenic GAMs, and the high cellular fractions found in the TME also suggest that there is a strong connection between NRP1 and tumor supporting cell populations." (PMID 30479695, 2018). "ACE, which was downregulated by NRP-1 in BT-474 cells has been reported to have pro-tumourigenic effects in various cancer types although its homologue ACE2 has anti-tumour roles." (PMID 29728077, 2018). "It has been reported that NRP1 mediates the infiltration of the Foxp3+ Treg cell into the tumor and regulates the immunological anti-tumor control in response to tumor-derived VEGF." (PMID 30532711, 2018). "Blood-borne rhodocetin-αβ triggers NRP1-MET signaling in tumor cells lining ATV/VM vessels, which consequently become increasingly permeable." (PMID 29854288, 2018). "This analysis demonstrated that the presence of VEGFR2/NRP1 trans‐complexes in tumor tissue is an independent marker for overall survival in PDAC patients (HR = 0.3, p = 0.008)." (PMID 30027561, 2018). "As tumor progression is dependent on angiogenesis, we also examined the potential consequence of VEGFR2/NRP1 trans‐complexes on the tumor compartment." (PMID 30027561, 2018). "The CRGDK/R truncated peptide, and NRP-1 complex with co-administration of anticancer drug facilitates tumour mass penetration." (PMID 30072655, 2018). "Among them, neuropilin-1 (Nrp1) was reported to exhibit tumor-promoting properties by enhancing the action of various growth factors." (PMID 30360368, 2018). "Altogether, our findings suggest that the tumor-promoting effects of HS3ST3B are dependent on the expression of Nrp1 in cancer cells." (PMID 30360368, 2018). "We observed a significant reduction in tumor cell proliferation when NRP1 acted in trans upon endothelial cell‐expressed VEGFR2." (PMID 30027561, 2018). "The binding to NRP-1 triggers an increase of the tumor tissue permeability and the peptide together with the cargo is internalized into the tumor." (PMID 29721153, 2018).
tumor (continued). "VEGFR and other VEGFR co-receptors of NRP-1 are involved in neoangiogenesis, tumor progression and differentiation by activating signaling pathways like PI3K/AKT, MAPK and SMAD." (PMID 29632646, 2018). "A recent study showed that a rationally designed SEMA3A mutant, that elicits NRP1-independent signals via the plexin A4 receptor, is an effective anti-tumor agent." (PMID 30532711, 2018). "Only in the cell lining of tumor VM vessels both NRP1 and MET were directly accessible from the vessel lumen (6A’)." (PMID 29854288, 2018). "The T cell-specific knockout of NRP1 blocks tumor infiltration of Tregs and restores the anti-tumor effect, eventually inhibiting tumor growth." (PMID 30532711, 2018). "As neuropilin 1 (Nrp1) has been identified as a critical factor for the stability of Treg cells and their suppression of anti-tumor immunity we tested Nrp1 expression on Tregs." (PMID 30469401, 2018). "NRP1 has been previously shown to promote tumorigenesis by enhancing angiogenesis and NRP1-positive cells have been reported to have tumor-initiating properties." (PMID 29867773, 2018). "Constitutive NRP1 expression by CD8+ T cells is sufficient to drive resistance to tumor vaccine-induced secondary tumor protection." (PMID 30400822, 2018). "NRP1 expressed on tumor cells can form VEGFR2/NRP1 trans‐complexes between tumor cells and endothelial cells which arrests VEGFR2 on the endothelial surface, thus interfering with productive VEGFR2 signaling." (PMID 30027561, 2018). "In the competitive binding test, it provided a piece of critical evidence that the effective targeting of the liposome to tumor cells was mediated by the specific binding of ligands and receptors of ανβ3-integrin and neuropilin-1." (PMID 30483904, 2018). "Engagement of Sema3A with Nrp1 and 2 and other receptors has shown to both enhance and reduce tumour cell motility and invasion in various preclinical models of cancer." (PMID 29720701, 2018). "As one example, neuropilin-1 has been shown to be a prognostic indicator for tumor metastasis in oral squamous cell carcinoma, prostate cancer, and malignant melanoma." (PMID 28672878, 2017). "NRP1 was also detected on tumor-infiltrating CD4+ and CD8+ T cells isolated from patients undergoing resection for metastatic melanoma and correlated with antigen experienced CD45RO phenotype." (PMID 29067024, 2017). "In GBM samples collected prior to bevacizumab treatment (bevacizumab-responsive) Nrp1 protein was robustly expressed in tumor cells as well as in intratumoral blood vessels." (PMID 28938007, 2017). "In this cross-sectional study, we found that circulating and tumor tissue expression of NRP-1 and circulating placental growth factor (PlGF) increase in advanced nodal and metastatic breast cancer compared with locally advanced disease." (PMID 28607365, 2017). "iRGD as a tumor-targeting and tumor-penetrating cyclic peptide can enhance the permeability of drug into tumor parenchymal via a tumor-specific and neuropilin-1-dependent manner." (PMID 28920712, 2017). "We have implicated CD91+CD11c+ cells in high-dose gp96-mediated suppression of tumour immunity and shown that gp96-conditioned pDCs have the capacity to engage and form stable interactions with Treg via Nrp1." (PMID 28561043, 2017). "In the current study, we demonstrated that the knockdown of NRP1 promotes tumor formation in KRASmt cells (PANC-1, A549, and AsPC-1) but suppresses tumor growth in KRASwt tumor cells (BxPC-3, H226)." (PMID 29018205, 2017). "These researchers observed that tumor cell-derived Sema3A binds to NRP1 on macrophages and negatively regulates their proliferation, while favoring M1 macrophage proliferation." (PMID 29067024, 2017). "The interaction with neuropilin-1 increases extravasation and energy-dependent endocytosis of the peptide and bystander molecules in a tumor-specific manner." (PMID 28839238, 2017).
tumor (continued). "Collectively, these data reveal that tumor growth, progression and recurrence following anti-vascular therapies such as bevacizumab are dependent, in part, on the Nrp1-TGFβ signaling pathway." (PMID 28938007, 2017). "Specifically, pDCs upregulate neuropilin-1 to enable the long term interactions of pDCs with Treg cells, thereby enhancing suppression of Th1 anti-tumour immunity." (PMID 28561043, 2017). "Here, we would like to elucidate the mechanism through which NRP1 plays opposing roles in oncogenesis and tumor progression." (PMID 29018205, 2017). "NRP-1 is a receptor for the iRGD peptide, which contains the C-terminal arginine motif and functions as a key mediator for tissue extravasation and tumor penetration." (PMID 29018206, 2017). "Vascular endothelial growth factor produced by the tumor induces the migration of Treg NRP1+ to the intratumoral environment, resulting in a local immunosuppression favorable to tumor growth." (PMID 28603524, 2017). "Both αv integrins and neuropilin-1 are overexpressed in numerous types of tumor tissues in vivo, including those of the central nervous system." (PMID 29018206, 2017). "Querying the open access IVY GBM Atlas Project (GAP) revealed that Nrp1 RNA is expressed in different tumor regions including the tumor vasculature." (PMID 28938007, 2017). "On the contrary, inhibition of NRP1, in the tumor cells containing KRASwt showed decreased tumor growth." (PMID 29018205, 2017). "In particular, low levels of soluble VEGFR1 expression in plasma and NRP1 expression on tumor cells are characteristics of a bevacizumab-responsive tumor." (PMID 29267273, 2017). "Nanoparticles directed by the tumor-homing peptide iRGD were selectively taken up by primary VS cultures in vitro via interactions with αvβ3/β5 integrins and neuropilin-1 (NRP-1)." (PMID 29018206, 2017). "We found that Nrp1 knockdown drastically inhibits tumor formation and attenuates tumor growth, when compared with the scramble control." (PMID 28887477, 2017). "Semaphorins were discovered as axonal growth cone guidance molecules; semaphorin 3B induced CXCL8 (IL-8) production by tumor cells in a Neuropilin-1 dependent manner, which recruited TAMs fostering a prometastatic environment surprisingly with tumor reduction." (PMID 28197019, 2017). "Doxorubicin liposomes conjugated to a NRP-1-specific tumor-penetrating peptide prolonged the survival in mice and effectively crossed the BBB." (PMID 28993773, 2017). "Nrp1 expression increases during tumor progression from low-grade to GBM, and is expressed in GBM cell lines and patient samples." (PMID 28938007, 2017). "Clusters of tumor cells that stained strongly positive for both αv integrin and NRP-1 were found throughout the tumor parenchyma in 11 different tumors." (PMID 29018206, 2017). "NRP1 knockdown enhanced cell viability and tumor growth and resulted in decreased SMAD2 phosphorylation." (PMID 29018205, 2017). "These include genes involved in hematological system development such as SETBP1 and NRP1 and putative tumor suppressor genes such as PARD3 and LRIG1." (PMID 28806978, 2017). "SEMA4A binding to NRP-1 has been established in T regulatory (Treg) immune cells, wherein it stabilizes the intra-tumoral Treg cells and enhances tumor immune evasion." (PMID 28607365, 2017). "The pre-planned correlative analyses of the AVAGAST trial identified baseline VEGF-A level and tumor neuropilin-1 expression as potential predictors of bevacizumab efficacy." (PMID 29228632, 2017). "The extracellular region of Nrp1 likely facilitates heterophillic interactions between tumor cells and endothelial cells in angiogenic blood vessels." (PMID 28938007, 2017). "The RGD motif initially targets the peptide to tumor vasculature by binding to αv integrins, and after a proteolytic cleavage step, the CendR motif interacts with neuropilin-1." (PMID 28839238, 2017).